TXNRD1 (thioredoxin reductase 1)
Diseases named in the same sentence as TXNRD1 in open-access papers (continued):
Sharing a sentence is not in itself a finding about the gene and the disease.
cancer (continued). "Among them, Cd34, protein tyrosine phosphatase, receptor type, F (Ptprf), Txnrd1, Pgd, Ugt1a1, Gpr137b, and dynein light chain Tctex-type 1 (Dynlt1) were connected in a molecular network of cancer-cell cycle-cell death." (PMID 22039513, 2011). "Targeting the activity of the thioredoxinsystem is considered a promising strategy in cancer treatment., The resulting arylation of the TXNRD1 catalytic CysSec-dyad by thegold compound leads to potent and irreversible enzyme inhibition inhuman colon carcinoma cancer cells." (PMID 41486557, 2026). "Our findings suggest that TXNRD1 blockade may enhance tumor progression in vivo through increased immune suppression, despite consistent anti-cancer activity in vitro and in immunocompromised models." (PMID 41300507, 2025). "Moreover, other small molecules targeting TXNRD1, such as Glaucocalyxin A (Glau A), promote cancer cell death through mechanisms like disulfide stress induced by glutathione depletion." (PMID 41154531, 2025). "Our findings reveal a paradoxical immunosuppressive effect of TXNRD1 inhibitors that may contribute to their limited efficacy in immunocompetent cancer models." (PMID 41300507, 2025). "Amongst the possible targets, the covalent inhibition of the cancer relevant selenoenzyme thioredoxin reductase 1 (TXNRD1) and of membrane transporters of water and glycerol (aquaglyceroporins, AQPs) by cyclometalated gold(III) compounds have been recently reported." (PMID 39771545, 2024). "The results from Nrf2 knockdown or thioredoxin reductase-1 (TrxR-1) experiments suggest that Nrf2- or TrxR-1-induced cell death might be related to the biphasic effects of SFN on cancer cell growth." (PMID 36768284, 2023). "The relevance of TXNRD1 has been increasingly acknowledged in recent years and has become the focus of understanding fundamental homeostatic cell functions as well as therapeutic approaches for cancer and other pathologies." (PMID 38086796, 2023). "Moreover, changes in the expression of SELENOP, Sep15, GPx1, GPx2, and TrXR1 (thioredoxin reductase 1) have been related to different forms of cancer." (PMID 37895024, 2023). "This makes TXNRD1 an appealing target for cancer therapy by disturbing cell redox balance." (PMID 37836684, 2023). "As activation of Akt is closely correlated with oncogenesis and metastasis of different cancers, TXNRD1 might promoted HCC development and metastasis through regulation the Akt signaling pathway." (PMID 36319631, 2022). "Pan-TXNRD inhibitors, such as auranofin, and specific TXNRD1 inhibitors have been developed in recent years, demonstrating their capacity to induce oxidative stress, to suppress cancer cell growth, and to kill cancer cells, hence confirming their therapeutic anticancer potential." (PMID 35158912, 2022). "Inhibition of TXNRD1 with AUR induced the release of ROS in cancer cells." (PMID 36578523, 2022). "TXNRD1, the cytosolic selenoprotein thioredoxin reductase 1 (TrxR1), served as a central regulator of the thioredoxin system and may be inhibited pharmacologically to achieve selective killing of cancer cells." (PMID 36524129, 2022). "In addition, we also investigated the effects of TXNRD1 on the key downstream effectors of the Akt signaling for cancer development." (PMID 36319631, 2022). "Therefore, similarly to the GPXs, it is likely that the high metabolic demand and increased oxidative stress results in cancer cells upregulating TXNRD1 to combat elevated ROS, deeming TXNRD1 an appropriate target for therapeutic development." (PMID 36358931, 2022). "Despite the fact that earlier studies by other authors have repeatedly shown that inhibition of GPX1, GPX 4, and TXNRD1 contributed to increased oxidative stress in cancer cells, our results indicate an increase in their expression under the influence of the studied agents." (PMID 35743086, 2022).
cancer (continued). "Moreover, high expression level of TXNRD1 has been reported in various cancers, such as breast, prostate and thyroid cancers, and is associated with aggressive tumor and poor prognosis." (PMID 36319631, 2022). "Recent evidence suggests that TXNRD1 may also be involved in ferroptosis resistance in cancer cells." (PMID 36358931, 2022). "In addition, the level of several selenoproteins, including TXNRD1 and GPX2, have been linked to different cancers." (PMID 35163318, 2022). "Several lines of evidence have supported the idea that TXNRD1 has cancer-preventive effects." (PMID 36319631, 2022). "TXNRD1 is involved in antioxidant defense and is correlated to cancer cells’ drug resistance." (PMID 35453395, 2022). "In addition, inhibitors of the antioxidant enzyme thioredoxin reductase 1, which is elevated in cancer, efficiently eliminated cancer cells including melanoma without affecting healthy cells." (PMID 36156348, 2022). "Notably, the inhibition of TXNRD1 by piperlongumine as well as TXNRD1 inhibitors auranofin and TRi-1, sensitize cancer cells to erastin-induced cell death." (PMID 35453395, 2022). "However, high expression level of TXNRD1 have been reported in many cancer cells, including neoplastic liver cells, suggesting that the increase in TXNRD1 is important for survival and the promotion of cancer progression." (PMID 36319631, 2022). "We, therefore, wanted to investigate whether it is possible to overcome ferroptosis resistance in cancer cells via inhibiting TXNRD1 by piperlongumine." (PMID 35453395, 2022). "Another finding was that thioredoxin reductase 1 (TxnRd1) could be induced by curcumin, and the sensitivity of cancer cells to radiation therapy is increased." (PMID 35645817, 2022). "Thioredoxin reductase 1 (TXNRD1) plays dual roles, because it can induce cancer and inhibit cancer." (PMID 34741349, 2021). "Although some studies have found that normal cells are more resistant to TXNRD1-targeted inhibition, there is still insufficient evidence from in vivo and clinical trials, and high levels of ROS may contribute to cancer mutagenesis." (PMID 33706760, 2021). "Combined with it being relatively easy to target and control the TXNRD1 gene, we believe this gene to be a promising cancer therapeutic target, and that its targeted inhibition may be effective in treating cancer." (PMID 33706760, 2021). "Previous studies identified TXNRD1 as a regulator of endocellular oxidative stress and a promoter of tumor development, with irreversible suppression of cytoplasmic TXNRD1 levels demonstrated as a novel direction for cancer treatment." (PMID 31384178, 2019). "Thus, TXNRD1 is often overexpressed in cancers and is a promising target for improved cancer therapy." (PMID 30820346, 2019). "Interestingly, TXNRD1 is upregulated in many human malignancies and promotes cancer progression, and attenuation of TXNRD1 levels effectively suppresses the growth of tumor cells." (PMID 31384178, 2019). "Thioredoxin reductase 1 is known to be overexpressed in most malignant cancer cells." (PMID 27065873, 2016). "This study suggests that blocking TXNRD1 could enhance cancer cell ferroptosis." (PMID 40916076, 2025). "Thus, the role of ROS, and to some extent NRF2 signaling, in shaping anti-tumoral immunity may explain inconsistent responses to auranofin in different models and guide more effective use of TXNRD1 inhibitors in cancer therapy." (PMID 41300507, 2025). "In addition, TXNRD1 is involved in iron death resistance of cancer cells." (PMID 38167017, 2024).
cancer (continued). "Additionally, Piper nigrum L. (Piperaceae), a known TXNRD1 inhibitor derived from long pepper, significantly enhances Erastin-induced lipid peroxidation in cancer cells, suggesting the potential of targeting TXNRD1 to promote ferroptosis as a therapeutic strategy." (PMID 39359249, 2024). "Similar to GPX4, many types of cancer cells show a particular dependence on TXNRD1 for survival and the enzyme has thus been the focus for drug development projects aimed at identifying inhibitors of TXNRD1, hypothesizing that such compounds may have anticancer properties [14,]." (PMID 37087975, 2023). "Modulation of TXNRD1 could influence the proliferation, invasion, and migration of carcinoma." (PMID 37999212, 2023). "Therefore, Nrf2 control of TXNRD1 expression in cancer may also be considered when targeting TXNRD1 to promote oxidative-stress induced cell death in cancer cells." (PMID 36358931, 2022). "Overexpression of TxnRd1 could enhance the anti-sensitivity effect of cancer cells." (PMID 35645817, 2022). "Thus, the dual role of TXNRD1 in cancers might depend on the stage of cancer initiation and development and on varied vulnerabilities of tissues to oxidative stress as well." (PMID 36319631, 2022). "Regulation of TXNRD1 could affect the proliferation, invasion and migration of carcinoma." (PMID 34906147, 2021). "Also Nrf2 targets may have dual roles in cancer which will here be discussed for the selenoproteins thioredoxin reductase-1 (TrxR1) and glutathione peroxidase-2 (GPx2)." (PMID 22654914, 2012). "Using genomic and proteomic data in DEPMAP database, we found that the expression of TXNRD1 and STAT3 genes and mTOR pS2448 protein were higher in CDDP resistance cancer cells compared to sensitive cancer cells to CDDP." (PMID 39859517, 2025). "For instance, TXNRD1 and NQO1, as redox stress-related enzymes, have been reported to be upregulated in various cancers and promote malignant progression." (PMID 41035672, 2025). "In most cancer species, the TXN and TXNRD1 high expression groups and the TXNIP low expression group had lower stromal and immune scores." (PMID 39744566, 2025). "We first evaluated the expression of TXN, TXNRD1, and TXNIP in pan-cancer data from TCGA and GTEx to further investigate the connection between the Trx system and malignancies." (PMID 39744566, 2025). "Analysis of cell lines in the DEPMAP showed that high levels (>median) of the TXNRD1 gene and increased levels of mTOR p-Ser2448 protein are statistically significantly correlated to resistance against CDDP in tested cancer cell lines." (PMID 39859517, 2025). "Cancer cells that express high levels of TXN1 and TXNRD1 are better able to withstand the effects of oxidative stress, proliferate, and even invade and metastasize." (PMID 39619695, 2024). "Thioredoxin reductase 1 (TR1), selenoprotein of 15 kDa (Sep15), and glutathione peroxidase 2 (GPx2) are the most studied members of this family in relation to cancer." (PMID 35267564, 2022). "This section will be focused on TXNRD1 as it has been the main TXNRD studied in cancer, and we will briefly comment on TXNRD2 and TXNRD3 and their relationship to cancer metabolism." (PMID 36358931, 2022). "The recent finding of the prioritization GPX4, TXNRD1, and SEPHS2 synthesis in cancer cells, favoring a cell proliferative phenotype, repurposes the selenoprotein synthesis hierarchy in cancer cells." (PMID 36358931, 2022). "TXNRD1, a form of TXN reductase, is upregulated in various cancers, including HCC, and is considered an adverse prognostic factor." (PMID 36544763, 2022).
cancer (continued). "Some genes were expressed at similar levels in different types of cancer, including GPX1, GPX4, TXNRD1, TXNRD2 and TXNRD3." (PMID 33706760, 2021). "The TXNRD1 and TXNRD3 genes are mainly related to poor prognoses, while other genes are related to good or poor prognoses depending on the type of cancer." (PMID 33706760, 2021). "The expression levels of the TXNRD1 and TXNRD3 genes were mainly related to a poor cancer prognosis." (PMID 33706760, 2021). "According to the results, MGST1, GPX3, SP1, TXNRD1, MAPK14, and SOD1 presented with CNV gains among various types of cancers." (PMID 34721758, 2021). "Through our analysis, we confirmed higher levels of GPX2 and TXNRD1, and lower levels of GPX1, SELENOF, and SELENOP in the cancer cell lines compared to normal epithelial cells, which has already been observed and reported in the literature." (PMID 32933107, 2020). "Thioredoxin reductase 1 (TR1), a protein belonging to the selenoprotein group, plays a role in both preventing and promoting cancer." (PMID 31443436, 2019). "Thioredoxin reductase 1 (TXNRD1) an NADPH-dependent oxidoreductase enzyme, best known for recycling thioredoxin to its reduced form, is overexpressed in a variety of human cancer cell lines and primary tumors, indicating its tumorigenic involvement." (PMID 27845352, 2016). "Consistent with a role for NFE2L2 in vitamin D-mediated cancer prevention, a number of NFE2L2 target genes were increased in RWPE1 cells after 1,25(OH)2D treatment, e.g. GPX3, HMOX1, AKR1C2, and TXNRD1." (PMID 20070897, 2010). "This review focuses on how thioredoxin-1 (TXN1), thioredoxin reductase-1 (TXNRD1), and members of the protein disulfide isomerase (PDI) family regulate thiol-disulfide balance at the cancer cell surface and how these alterations can be exploited for theranostic applications." (PMID 41903319, 2026). "Cancer cells typically exhibit elevated reactive oxygen species (ROS) levels that are counterbalanced by upregulation of antioxidant systems, including TXN1/TXNRD1 and PDIs, which also act at the cell surface." (PMID 41903319, 2026). "Our results demonstrate that exogenous SELENOV downregulated TXNRD1 and TXNRD3 mRNA expression, which may represent an important anticancer effect since both enzymes are frequent pharmacological targets in various cancer therapies." (PMID 41463386, 2025). "The results of our study suggest that the Trx system, which consists of TXN, TXNRD1, and TXNIP, may be useful for the early diagnosis and monitoring of cancer." (PMID 39744566, 2025). "It should be emphasized that the two opposing roles of TXNRD1 in cancers, prevention/promotion, is not paradoxical." (PMID 36319631, 2022). "Regrettably, except for DHODH and TXNRD1, the relevance of other candidate genes to human cancer has not been reported." (PMID 36524129, 2022). "The ubiquitously expression of GPX1,GPX4,TXNRD1 and TXNRD2 in humans has been reported in previous studies, and our study further confirmed these genes were also ubiquitously expressed in different types of cancer." (PMID 33706760, 2021). "The association of SNPs in TXNRD1 and TXNRD2 with disease risk was only observed in advanced stage or high grade cancers and not in localized low-grade cases." (PMID 23133653, 2012). "When we studied TXNRD1 expression in ERBB2-status-positive versus ERBB2-status-negative carcinomas, significantly higher levels were obtained for ERBB2-status-positive tumors in all three individual study cohorts." (PMID 20584310, 2010). "The negative correlations to TrxR (TXNRD1) expression by reported TrxR-Trx inhibitory compounds, as well as by compounds with very strong similarities in anti-cancer activity, suggest that the cytotoxicity of these compounds is greater when TrxR levels are low." (PMID 37446864, 2023). "However, several studies also indicated that some selenoproteins, namely important cellular redox regulators TXNRD1, SELENOF, and GPx2, may both prevent and promote cancer." (PMID 34829750, 2021).
cancer (continued). "However, while GPX1 and GPX4 were more highly expressed in tumor tissue from the Czech and Irish cancer groups, respectively, TXNRD1 was not significantly different in any of our tested cohorts." (PMID 30469315, 2018). "Finally, by testing the relationship between the expression levels of these two families of selenoprotein genes in NCI-60 cell lines and drug sensitivity, we found that the TXNRD1, GPX1, GPX2, and GPX3 genes may play a role in the drug sensitivity or drug resistance of cancer cells." (PMID 33706760, 2021).